SHH (sonic hedgehog signaling molecule)
Diseases named in the same sentence as SHH in open-access papers (continued):
Sharing a sentence is not in itself a finding about the gene and the disease.
medulloblastoma (continued). "Since Group 3 and 4 tumours were associated with different survival rates of patients in previous studies, we hypothesised that tumour enhancement pattern alone may serve as a useful prognostic marker in the biologically relevant non-WNT/SHH group of medulloblastoma." (PMID 25862008, 2015). "Histopathology confirmed a desmoplastic/nodular medulloblastoma, non-wingless (WNT)/non-sonic hedgehog (SHH)." (PMID 41710837, 2026). "The final histological diagnosis was classic medulloblastoma CNS WHO Grade 4, and genetic profiling confirmed the non-WNT/non-SHH molecular subgroup." (PMID 41257104, 2025). "As one of the most common malignant brain tumors in children, the World Health Organization classified medulloblastoma (MB) into four subtypes on the basis of genomics and DNA methylation: WNT, SHH, and non-WNT/non-SHH (Group 3 and Group 4)." (PMID 40229260, 2025). "Our analysis of bulk RNA-seq from CT and non-CT medulloblastomas emphasised differences in gene expression and activated pathways, in particular regarding MYC driven transcription, SHH signalling, and proliferation." (PMID 39580568, 2024). "A recent genetics-based study defined four main subgroups of medulloblastoma (i.e., WNT-activated, SHH-activated, and non-WNT/non-SHH, including Group 3 and Group 4) based on transcriptional profiling." (PMID 39518048, 2024). "Groups 3 and 4 represent about two-thirds of all pediatric medulloblastoma cases and have now been grouped together as non-WNT/non-SHH." (PMID 37943476, 2023). "The 2021 WHO classification of tumors of the central nervous system (CNS) lists MYCN among the genes characteristically altered in diffuse pediatric-type glioma, spinal ependymoma, as well as SHH-activated and non-WNT/non-SHH medulloblastoma." (PMID 37407554, 2023). "Developmental gene expression data from medulloblastoma (MB) suggest that WNT-MB originates from the region of the embryonic lower rhombic lip (LRL), whereas SHH-MB and non-WNT/non-SHH MB arise from cerebellar precursor matrix regions." (PMID 37835571, 2023). "Methylation and “omics” studies have further identified new subgroups and currently, there are two different WNT subgroups, four different SHH subgroups, and eight subgroups of non-WNT/non-SHH medulloblastoma." (PMID 38132264, 2023). "We included both spatial and temporal (primary and relapse) medulloblastoma samples in this analysis and studied the methylation family (e.g. non-WNT/non-SHH), class (e.g. Group 4) and subclass (e.g. subclass VIII) level." (PMID 35842717, 2022). "The latest WHO classification of tumors of the central nervous system simplified medulloblastoma into three subgroups—WNT, SHH and non-WNT/non-SHH." (PMID 36303547, 2022).
medulloblastoma (continued). "CSCs in FSmoM2;hGFAP-cre medulloblastomas depend on bFGF/EGF and not SHH, similar to their cell of origin (NSCs), and they are insensitive to SHH inhibition, even though the SHH pathway is highly activated in bulk tumor cells in this model." (PMID 36688010, 2022). "The molecular classification of medulloblastomas (grade 4) currently acknowledges four subtypes: WNT-activated, SHH-activated, and non-WNT/non-SHH subgroups including “group 3” and “group 4”." (PMID 33498680, 2021). "Whereas, adults with SHH-driven medulloblastoma have more favorable overall survival (OS) than non-WNT/non-SHH tumors, adults with WNT-driven medulloblastoma do not show the favorable outcomes of pediatric patients." (PMID 32676456, 2020). "Ninety three pediatric medulloblastoma tumor samples were retrospectively stratified into three molecular subgroups; WNT, SHH and non-WNT/non-SHH, using immunohistochemistry and Multiplex Ligation Probe Amplification." (PMID 31471537, 2019). "This cohort of 136 samples consisted of 28 (21%) classified as WNT, 17 (13%) as SHH, and 91 (67%) as non-WNT/non-SHH (we considered Group3 and Group4 medulloblastoma together in our analysis because of their similar molecular and clinical features)." (PMID 30392813, 2018). "SHH mediators GLI2 and GLI3 are significantly upregulated in SHH-MB, but GLI3 is not upregulated in the larger pool of medulloblastomas, and there is only weak evidence that GLI2 is upregulated." (PMID 29099739, 2017). "The increase in CD4 T cells predicts a better prognosis in medulloblastoma patients, particularly within the SHH and non-WNT/non-SHH subgroups, and they may serve as a potential therapeutic target for medulloblastoma." (PMID 40575173, 2025). "Medulloblastoma is the most common primary pediatric malignancy of the central nervous system, which is divided into wingless (WNT), sonic hedgehog (SHH) and non-WNT/non-SHH molecular subgroups." (PMID 35860588, 2022). "Notably, cilia are only found in SHH and WNT subgroups but not present in other medulloblastoma subgroups thus underscoring the functional importance of cilia in tumors that are driven by SHH and WNT signaling." (PMID 35295905, 2022). "At least four distinct subtypes comprise medulloblastoma: WNT-activated, SHH-activated, non-WNT/non-SHH group 3, and non-WNT/non-SHH group 4, with group 3 patients carrying c-Myc overexpression having the worst prognosis, as reflected in the current revision of the WHO classification." (PMID 31788346, 2019).
medulloblastoma (continued). "To examine the utility of BarTeL mice in producing medulloblastomas modeling the SHH subgroup, we injected cerebella of BarTeL pups at 1–3 days of age with nontumorigenic chicken DF-1 cells producing either RCAS-ShhN or RCAS-MycnT50A,S54A, or with DF-1 cells producing both viruses." (PMID 27310018, 2016). "PTGER4 expression in the SHH subgroup was increased in comparison to its expression in Group 3 and Group 4 tumors (t-probabilities = 1.6e-6, 2.7e-8, respectively), but not WNT tumors, in the Toronto series of medulloblastoma patients." (PMID 24252460, 2013). "The impact of the molecular subgroups within medulloblastoma may also apply to outcomes after surgical resection, with a recent study demonstrating more aggressive surgery beyond subtotal resection does not affect progression-free survival for patients with WNT, SHH, or G3 tumors." (PMID 31948065, 2020).
pancreatic cancer (87 papers, 2011 to 2026). "Another study reported that loss of Hh ligand co-receptors, GAS1 and BOC, in mouse embryonic and pancreas cancer-associated fibroblasts (CAFs) led to partial suppression of pathway response to SHH and increased angiogenesis." (PMID 32108165, 2020). "Recent studies have shown that the SHH pathway is upregulated in a subset of lung adenocarcinoma with EGFR mutation, and inhibition of the SHH pathway can also enhance the activity of EGFR inhibitor gefitinib in pancreatic cancer cells." (PMID 33291316, 2020). "Soluble mediators like IL-6, IL-8, IL-1β, TGF-β, TNF-α, VEGF, SHH, etc. have been implicated in pancreatic cancer carcinogenesis." (PMID 32707920, 2020). "Enhanced activation of SHH signaling has been linked to the progression of breast and pancreatic cancers, and selective HHAT chemical probes and several inhibitors have been developed as potential therapeutic agents." (PMID 30338036, 2018). "Clinical specimens have shown that SHH, induced by hypoxia via a ligand-independent mechanism, is overexpressed in pancreatic cancer cells and activates PSCs to secrete high levels of perineural invasion-associated molecules to promote perineural invasion in pancreatic cancer." (PMID 30060755, 2018). "The Sonic Hedgehog (SHH) signaling system is a key factor in the development of pancreatic cancer, influencing the tumor microenvironment and encouraging the growth of cancer cells." (PMID 39900571, 2025). "Overexpression of the sonic hedgehog (SHH), one of three ligands that regulate the hedgehog signaling pathway, has been observed in both pre-invasive and invasive epithelium in human pancreatic cancer samples." (PMID 39941724, 2025). "One of the signals that maintains the active state of pancreatic tumor stroma is the developmental protein Sonic Hedgehog protein (SHH)." (PMID 38672552, 2024). "SHH was found to be effective in reducing tumor size and angiogenesis in a mouse model of pancreatic cancer." (PMID 36900220, 2023). "Further studies have shown that hamster N-terminal Sonic hedgehog (SHH) is 99% identical to human, while N-SHH promotes desmoplasia in human pancreatic cancer." (PMID 36923404, 2023). "Clinical trials inhibiting Hedgehog signaling have yielded moderate results, at best, possibly influenced by roles of SHH signaling in restraining pancreatic cancer cell progression." (PMID 37046676, 2023). "One of the HH pathway ligands, Sonic hedgehog (SHH), was expressed by a majority (70%) of pancreatic cancers, while also being present in CSCs of pancreatic ductal adenocarcinoma." (PMID 37108193, 2023). "The de-regulation of SHH was believed as a vital aspect that can continue the development of pancreatic cancer." (PMID 36865478, 2023). "SHH signaling in CAFs inhibits Ras-dependent tumor progression in pancreatic intraepithelial neoplasia and pancreatic cancer." (PMID 37046676, 2023). "Still, upstream regulators of NNMT in cancer were shown to be diverse, as in BRCA1 for ovarian cancer, HNF1β for thyroid cancer, and SHH for pancreatic cancer." (PMID 36750850, 2023). "Gemcitabine-resistant pancreatic cancer cells display a higher expression of SHH, SMO, and GLI1 in comparison with parental cells." (PMID 35154464, 2022). "A component of this pathway Sonic HH (SHH), is increased more than 40-fold in pancreatic cancer stem cells responsible for tumour recurrence." (PMID 36591282, 2022). "The SHH pathway also contributes to the development and progression of pancreatic cancer, through maintaining stemness features of the pancreatic CSCs and enhancing cellular proliferation through NF-κB-mediated activation of the SHH pathway." (PMID 36428556, 2022). "Targeted inhibition of SHH can promote the TME of pancreatic cancer, and thus improve the response of pancreatic cancer cells to chemotherapy." (PMID 36118526, 2022). "For instance, while SHH inhibition appears to limit metastasis in orthotopic models of pancreatic cancer, deletion of stromal SHH accelerates disease." (PMID 33918004, 2021).
pancreatic cancer (continued). "SHH is involved in tumor metastasis in basal cell carcinoma, ovarian cancer, cervical cancer, breast cancer, gastric cancer, and pancreatic cancer and is related to drug resistance and survival of cancer." (PMID 34956562, 2021). "We reported increased expression and secretion of Sonic hedgehog (SHH) protein in pancreatic cancer cells upon exposure to hypoxic stimuli." (PMID 34135469, 2021). "The SHH-specific mouse antibody 5E1 binds tightly to the SHH metal-binding site, overlapping with HHIP61, and has been shown to inhibit SHH activity in vivo and to reduce tumour growth in a pancreatic cancer mouse model." (PMID 34887403, 2021). "Mouse models (subcutaneous and orthotopic implantation) using a pancreatic tumor cell line showed that cells can secrete SHH, and that expression of SHH was high in a transformed primary cell line." (PMID 31979397, 2020). "A caveat of both studies is that SHH is only one of three HH ligands, and at least two (Shh and Ihh) are expressed in pancreatic cancer." (PMID 33198201, 2020). "The activated SHH in pancreatic tumors enhances angiogenesis, lymphangiogenesis, and metastasis to produce a pro-angiogenic effect and to promote metastasis in the stroma." (PMID 31979397, 2020). "SHH is therefore proposed as a target in the treatment of SHH-dependent pancreatic cancer and breast cancers." (PMID 31979397, 2020). "These researchers used a mouse model of pancreatic cancer and found that SHH signaling activation is present in the SHH-expressing tumor epithelium surrounding the stroma." (PMID 31979397, 2020). "Bailey and colleagues revealed that Sonic Hedgehog (SHH) expression promotes a desmoplastic reaction in pancreatic cancer." (PMID 32707920, 2020). "Using quantitative RT-PCR to examine tissue samples of both primary or metastatic human pancreatic cancer, activation of the SHH pathway in the tumor stroma was found." (PMID 31979397, 2020). "It is also reported that Shh and Gli are overexpressed in pancreatic cancer, which suggested that SHH and GLI can be used as prognostic indicators." (PMID 31898580, 2019). "Sonic hedgehog (SHH) signaling is one of the major signaling pathway activated in pancreatic cancer." (PMID 31083682, 2019). "The SHH protein secreted from pancreatic cancer cells under hypoxic conditions promoted the growth of fibroblasts by stimulating their Sonic hedgehog signaling pathway." (PMID 29535824, 2018). "Our result is not necessarily consistent with a previous report that the growth of pancreatic cancer cells was enhanced not only when treated with recombinant SHH proteins but also when transiently transfected with an SHH expression vector." (PMID 29535824, 2018). "Taken together, these results indicate that both the expression and secretion of SHH were upregulated in pancreatic cancer cell lines under hypoxic conditions." (PMID 29535824, 2018). "Specifically, the mature form of Sonic hedgehog protein (SHH) is secreted from pancreatic cancer cells after removal of the signal peptide and autocatalytic processing." (PMID 29535824, 2018). "Among these signaling pathways activating PSCs, SHH expression in pancreatic cancer cells is induced by KRAS by the activation of nuclear factor-κB (NFκB)." (PMID 30060755, 2018). "We demonstrated that SHH proteins secreted from pancreatic cancer cells activated the Sonic hedgehog pathway of fibroblasts and accelerated the proliferation of fibroblasts in a paracrine manner." (PMID 29535824, 2018). "Inhibition of pancreatic cancer-derived SHH, an important molecule in embryonic development, reduces lymphangiogenesis and lymph node metastasis in a pancreatic cancer mouse model." (PMID 30060755, 2018). "Hypoxic induction of the SHH gene expression was observed in other pancreatic cancer cell lines, such as PANC-1, SUIT-2, CFPAC-1, and BxPC-3." (PMID 29535824, 2018).